KLHL28 (kelch like family member 28)
Synonyms: BTBD5; FLJ20081
Tractability: Small molecule: it belongs to a druggable protein family. PROTAC: ubiquitination databases record sites on it.
Gene: Protein-coding gene on chromosome 14 (44,924,324 to 45,042,322, reverse strand). Ensembl gene ENSG00000179454.
Subcellular location (Human Protein Atlas): Cytosol
Gene Ontology:
Molecular function: ubiquitin-like ligase-substrate adaptor activity
Biological process: proteasome-mediated ubiquitin-dependent protein catabolic process
Cellular component: Cul3-RING ubiquitin ligase complex; cytoplasm
Genetic constraint (gnomAD): Loss-of-function variants: 21 observed, 47.09 expected, observed/expected ratio (o/e) 0.45, 90% interval 0.31 to 0.64. The upper end of that interval is the gene's LOEUF score, 0.64, which puts it in group 2 of 6, group 1 being the genes least tolerant of losing a copy. Missense variants: 525 observed, 735.84 expected, observed/expected ratio (o/e) 0.71, 90% interval 0.66 to 0.77. Synonymous variants: 242 observed, 256.32 expected, observed/expected ratio (o/e) 0.94, 90% interval 0.85 to 1.05.
Homologues: Orthologues: chimpanzee KLHL28 (99% identical), macaque KLHL28 (99% identical), dog KLHL28 (99% identical), pig KLHL28 (99% identical), rabbit KLHL28 (98% identical), guinea pig KLHL28 (98% identical), rat Klhl28 (98% identical), mouse Klhl28 (97% identical), tropical clawed frog klhl28 (87% identical), zebrafish KLHL28 (71% identical). Paralogues in human: KLHL20 (41% identical), KLHL17 (39% identical), KLHL1 (37% identical), KLHL3 (37% identical), KLHL5 (37% identical), KLHL12 (36% identical), KLHL4 (36% identical), KLHL18 (36% identical), KLHL2 (36% identical), KEAP1 (34% identical), KLHL10 (34% identical), IPP (32% identical), and 42 more.